GUCY1B2 (guanylate cyclase 1 soluble subunit beta 2 (pseudogene))
Synonyms: GUCY1B2P; GC-SB2
Gene: Transcribed unitary pseudogene on chromosome 13 (51,006,991 to 51,062,894, reverse strand). Ensembl gene ENSG00000123201.
Subcellular location: Cytoplasm
Diseases named in the same sentence as GUCY1B2 in open-access papers:
GUCY1B2 is named in the same sentence as 2 diseases in open-access papers, as found by Europe PMC text mining. Sharing a sentence is not in itself a finding about the gene and the disease. The quoted sentences say what the papers report.
diabetic cardiomyopathy (1 paper, 2024). Diabetic cardiomyopathy is a disorder of the heart muscle in people with diabetes. "In contrast, the significant regulation of the diabetic cardiomyopathy gene Gsk3b (glycogen synthase kinase 3 beta, x = −1.490, CUT = 1.341) and the purine metabolism gene Gucy1b2 (guanylate cyclase 1, soluble, beta 2; x = 1.490, CUT = 1.426) would have been neglected." (PMID 38534766, 2024).
cancer (1 paper, 2015). A tumor composed of atypical neoplastic, often pleomorphic cells that invade other tissues. "However, some have been reported playing critical roles in cancer, such as H19, GUCY1B2, MEG3 and AKR7L." (PMID 25928635, 2015).